IL6 (interleukin 6)
Diseases named in the same sentence as IL6 in open-access papers (continued):
Sharing a sentence is not in itself a finding about the gene and the disease.
acute respiratory distress syndrome (continued). "There is a report that high levels of IL6 in bronchoalveolar lavage fluid (BALF) were found in patients who died from acute respiratory distress syndrome compared to those who survived, suggesting that the levels of IL6 are associated with severity of lung inflammation in patients." (PMID 21826229, 2011). "In the context of infectious diseases like COVID-19, vitamin K inhibits pro-inflammatory cytokines (IL-6, IL-1β, and TNF-α) and enhances the integrity of alveolar-capillary membranes reducing the risk of acute respiratory distress syndrome (ARDS)." (PMID 40718363, 2025). "Although WBC levels decreased to 9.89×109/L, IL-6 levels increased significantly to 69.864 pg/mL, and arterial blood gas analysis indicated mild acute respiratory distress syndrome (ARDS) with an oxygenation index of 295 mmHg." (PMID 40491912, 2025). "A cytokine storm, characterized by excessive production of pro-inflammatory cytokines—particularly TNF-α, IL-6, and IL-1β—can trigger multiorgan damage and acute respiratory distress syndrome (ARDS)." (PMID 40807350, 2025). "IL-6 has been found to be significantly elevated in severe diseases such as sepsis, acute respiratory distress syndrome (ARDS), and even COVID-19, most recently." (PMID 39108599, 2024). "The well-established cytokine release syndrome in acute Covid infection, clinically manifesting as acute respiratory distress syndrome (ARDS), is characterized by sympathetically mediated pro-inflammatory cytokine cascade (driven by IL-6)." (PMID 37255928, 2023). "In particular, overproduction of IL‐6 is a valuable marker of poor outcomes in SARS‐CoV‐2 patients with acute respiratory distress syndrome (ARDS)." (PMID 37025056, 2023). "Increased proinflammatory cytokines such as IL-1, IL-2, IL-6, IL-7, IL-10, are frequently observed in many COVID-19 patients, which is closely related to the acute respiratory distress syndrome (ARDS), multiorgan failure and other severe symptoms." (PMID 37228604, 2023). "A considerable proportion of individuals suffer from severe pneumonia, and some even develop acute respiratory distress syndrome (ARDS), which is believed to be triggered by cytokine storms (IL-6, IL-1, and TNF-α)." (PMID 37251406, 2023). "Massive systemic release of pro-inflammatory mediators such as interleukin (IL)-1β, IL-2, IL-6, IL-7, IL-10, tumor necrosis factor-α (TNFα), granulocyte colony-stimulating factor (G-CSF), etc., also known as cytokine storm, contributes to the acute respiratory distress syndrome (ARDS)." (PMID 35888733, 2022). "Excessive IL-6, IL-1β, and TNFα levels along with increased recruitment of immune cells in the airways contribute to epithelial damage and acute lung injury, driving the development of acute respiratory distress syndrome (ARDS), leading to severe vascular leakage and pulmonary edema." (PMID 35846766, 2022). "Higher serum levels of Gal-3 were related to a tendency of severe acute respiratory distress syndrome (ARDS) development, and alongside IL-6 and CRP, Gal-3 was demonstrated to be the best predictive power for mortality outcome." (PMID 35204790, 2022). "The significant elevation of IL6, a pro-inflammatory cytokine, can lead to a “cytokine storm” and result in acute lung injury, acute respiratory distress syndrome (ARDS), MODS or even multiple organ failure (MOF)." (PMID 33664741, 2021). "Increased production of interleukin (IL-1, IL-6, IL-8) cytokines in plasma resulting in dyspnea, acute respiratory distress syndrome (ARDS), and death." (PMID 33498861, 2021). "Furthermore, many ICU ventilated cases have acute respiratory distress syndrome (ARDS) which in severe cases may be linked to IL-6 elevations and given the role of IL-6 in tissue repair, the outcome of tocilizumab on ventilated ARDS cases is worthy of consideration." (PMID 34501738, 2021).
acute respiratory distress syndrome (continued). "Several studies revealed that high circulating IL-6 in trauma patients was associated with multi-organ dysfunction syndrome (MODS), acute respiratory distress syndrome (ARDS), and mortality." (PMID 34073768, 2021). "Acute respiratory distress syndrome (ARDS) generates a cytokine storm by eliciting the overproduction of many inflammatory mediators including IL-6, and contributes to the mortality and severity of a COVID infection." (PMID 34538093, 2021). "The proportion of LOX-1- or CD123-expressing ImNs is positively correlated with clinical severity, cytokine storm (IL-1β, IL-6, IL-8, TNFα), acute respiratory distress syndrome (ARDS), and thrombosis." (PMID 34616409, 2021). "SARS-CoV considered as beta-coronaviruses can lead to acute respiratory distress syndrome (ARDS) due to uncontrolled cytokine release such as IL-6." (PMID 33138692, 2020). "Therefore, although exaggerated levels of IL-6 have been observed in adult patients with acute respiratory distress syndrome due to massive lung tissue damage, IL-6 also likely provides protection from infections with influenza virus and other respiratory viruses." (PMID 33193346, 2020). "The level of respiratory distress, up to the development of an Acute Respiratory Distress Syndrome (ARDS) eventually requiring mechanic ventilation, has been directly related to the release of inflammatory cytokines, mainly IL-6." (PMID 32993497, 2020). "The elevated expression of TNF-α and IL-6 is an important step in the pathogenesis of ALI and acute respiratory distress syndrome." (PMID 29069220, 2017). "However, excessive TNF-α synergizes with IL-6 and IL-1β, leading to increased vascular permeability, pulmonary edema, and multi-organ damage, especially in acute respiratory distress syndrome (ARDS)." (PMID 41592028, 2026). "This process triggers the excessive production of proinflammatory cytokines, including IL-6, IL-1β, and TNF-α, contributing to acute respiratory distress syndrome (ARDS), which is characterized by pulmonary edema, hypoxemia, and respiratory failure." (PMID 41521316, 2026). "Coronavirus disease 2019 (COVID-19)-induced acute respiratory distress syndrome (ARDS) is characterized by hyperinflammation and elevated pro-fibrotic cytokines such as IL-6, IL-7, GM-CSF, MCP, and macrophage inflammatory protein-1α (MIP1α)." (PMID 40343260, 2025). "The excessive production of IL-6, TNF, and IL-1β in glycolysis-driven immune cells results in widespread tissue damage, endothelial dysfunction, and acute respiratory distress syndrome (ARDS)." (PMID 40453076, 2025). "IL‐6 has gained prominence for its involvement in the cytokine storm observed in severe COVID‐19 cases, a phenomenon that contributes to the development of acute respiratory distress syndrome (ARDS) and subsequent organ damage." (PMID 40135792, 2025). "Cytokines, such as interleukin-6 (IL-6), interleukin-1 (IL-1), interleukin-17 (IL-17), and tumor necrosis factor-alpha (TNF-α) play a significant role in lung damage in acute respiratory distress syndrome patients through impairment of respiratory epithelium." (PMID 40429912, 2025). "The infection triggers the excessive production of pro-inflammatory cytokines (such as IL-6, TNF-a, IL-1, and CRP), thereby inducing acute respiratory distress syndrome." (PMID 40260091, 2025). "The primary complication of SARS-CoV-2 infection, Acute Respiratory Distress Syndrome (ARDS), stems from a ‘cytokine storm’ triggered by the uncontrolled release of proinflammatory cytokines and chemokines from immune cells, including IL-6, TNF-α, IFN-γ, and others." (PMID 39245237, 2025). "Interleukin-6 induces shortness of breath, pulmonary fibrosis, and a reduction in oxygen saturation and results in the development of acute respiratory distress syndrome (ARDS), multiple organ failure, and death." (PMID 39195858, 2024).
acute respiratory distress syndrome (continued). "The second potential adverse outcome is hyperinflammation, characterized by high levels of C-reactive protein (CRP), interleukin (IL)-6, and tumor necrosis factor alpha (TNF-α), which can increase the risk of PLWH developing acute respiratory distress syndrome (ARDS)." (PMID 39597537, 2024). "We can observe the elevating IL-6, TNF and IFNƳ serum levels in patients with severe COVID pneumonia, especially complicated by acute respiratory distress syndrome ARDS." (PMID 37608339, 2023). "In a cohort of 35 acute respiratory distress syndrome (ARDS) and 13 sepsis patients, 3 patients showed anti-IL-6 auto-antibodies, two anti-IFNω auto-antibodies, two anti-IFNγ auto-antibodies, and one anti-IL-1α auto-antibodies." (PMID 38203686, 2023). "It has been confirmed to alleviate lung injury of acute respiratory distress syndrome by down-regulating the mRNA expression of inflammatory factors such as TNF-α, IL-6, and IL-1β, as well as by reducing neutrophil infiltration." (PMID 37547679, 2023). "More specifically, patients with acute respiratory distress syndrome (ARDS), ICU hospitalization, and severe symptoms had 2.9-fold higher levels of IL-6." (PMID 37189760, 2023). "Ang II plays a role in adaptive immunity during acute respiratory distress syndrome (ARDS) development by inducing proinflammatory IFN-γ, TNF-α, and IL-6 production." (PMID 35955801, 2022). "They concluded that children with lowest serum concentrations of IL6 and TNFα, cytokines associated with acute respiratory distress syndrome (ARDS), recovered without sequelae." (PMID 35626859, 2022). "CRS is an acute inflammatory syndrome characterized by fever and multi-organ dysfunction associated with raised inflammatory markers including C-reactive proteins (CRP) and Interleukin-6 (IL-6) which can result in acute lung injury and acute respiratory distress syndrome (ARDS)." (PMID 34650867, 2021). "The excessive production of pro-inflammatory cytokines, such as TNF and IL-6, further induces endothelial damage and lung injury, and its more severe form, Acute Respiratory Distress Syndrome (ARDS), that can result in respiratory and/or multi-organ failure and death." (PMID 34576169, 2021). "Elevated early pro-inflammatory cytokines like interleukins (IL2, IL6, and IL10) and Tumor necrosis factor (TNF) in ICU subjects reflect the cytokine storm leading to acute respiratory distress syndrome (ARDS) and progressive multiple organ failure." (PMID 33869282, 2021). "4-OI was also found play an extremely important role in alleviating acute lung injury (ALI) or acute respiratory distress syndrome (ARDS) by inhibiting the expression of the downstream inflammatory cytokines (IL-β, IL-6, and TNF-α) and ROS to increase the activity of antioxidants in lung tissue." (PMID 34055739, 2021). "Several additional clinical trials have been registered, and similarly, antibodies against the interleukin 6 (IL-6) receptor and IL-6 itself are under development for the treatment of the acute respiratory distress syndrome (ARDS) suffered by some COVID-19 patients." (PMID 34575589, 2021). "TLR signaling pathways promote the production of IFN-α, IFN-β, IL-6, TNF, IFN-γ, CCL5, and IFN-stimulated genes, which are produced during acute respiratory distress syndrome (ARDS) and viral infections." (PMID 33953641, 2021). "Numerous studies suggest that the curcuminoids inhibit proinflammatory cytokines such as IL-1, IL-6, IL-8, and TNF-α, prevent acute respiratory distress syndrome (ARDS), and repair the COVID-19-induced cellular damage." (PMID 34671412, 2021). "PLA2G2A (type-II secretory phospholipase A2/sPLA2), an enzyme associated with acute respiratory distress syndrome (ARDS), PLA2G2A expression was increased under both IL-6 and IL-6 trans-signalling conditions and amplified inflammatory responses in human airway smooth muscle cells." (PMID 32874197, 2020).
acute respiratory distress syndrome (continued). "Acute kidney injury (AKI) is the most frequent extra-pulmonary organ failure in acute respiratory distress syndrome (ARDS), according to a recently confirmed bidirectional organ crosstalk, possibly IL-6 mediated." (PMID 32838177, 2020). "The GSK3B inhibitor reduces the production of IL-6, TNFα, IL-17, and IL-1β in the BALF of mice with lipopolysaccharide-induced acute respiratory distress syndrome, thus relieving the lung injury." (PMID 31466385, 2019). "Serum and bronchoalveolar fluid IL-6 are increased in patients with acute respiratory distress syndrome (ARDS) and predict prolonged mechanical ventilation and poor outcomes, although the role of intra-alveolar IL-6 in indirect lung injury is unknown." (PMID 23667439, 2013). "Moreover, additional predictors of mortality at admission to an intensive care unit (ICU) have been identified as acute respiratory distress syndrome (ARDS), interleukin (IL)-6, serum albumin, and D-dimer levels, as well as chest CT severity score." (PMID 35208631, 2022). "The resulting acute respiratory distress syndrome (ARDS) and extrapulmonary multi-organ dysfunction are provoked by the excessive production of pro-inflammatory cytokines (IL-6, CXCL8) and chemokines (CXCL10, CCL5, CCL2), a phenomenon also referred as cytokine storm." (PMID 35013790, 2022). "Moreover, patients who subsequently developed certain adverse clinical outcomes, including the cytokine storm, ICU admission, acute respiratory distress syndrome (ARDS), or death tended to have higher IL-6 levels than healthy cohorts." (PMID 35464491, 2022). "Furthermore, other research has also shown that lnc‐KCNQ1OT1 is able to negatively regulate IL‐6, TNF‐α, and IL‐10 expression in acute respiratory distress syndrome." (PMID 34761437, 2021). "Normal levels of metabolic markers were reported after balloon deflation, with some transient inflammatory mediator activation (IL6) particularly in the 60- and 90-min groups as well as a tendency to require more vasopressor support (NS) and to develop acute respiratory distress syndrome (ARDS, NS)." (PMID 33407759, 2021). "An immunomodulant is administrated in the presence of ARDS (Acute Respiratory Distress Syndrome), or progressive worsening of respiratory activity and MIS (Multisystem Inflammatory Syndrome), an increase of IL-6 and/or D-dimer and/or ferritin and/or C-reactive protein." (PMID 34576859, 2021). "Acute respiratory distress syndrome (ARDS) is the leading cause of death in COVID-19 patients, and DPP4 inhibitors may be a new treatment approach because they can decrease the production of inflammatory factors such as IL-1β, TNF-α, and IL-6." (PMID 34955820, 2021). "NLRP3 inflammasome overactivation produces excessive IL-1β and downstream cytokines such as IL-6 and TNF-α, are also observed in acute respiratory distress syndrome (ARDS), ventilator induced lung injury (VILI), and disseminated intravascular coagulation (DIC)." (PMID 34150848, 2021). "A recombinant human ACE2 (APN01) was found to decrease the levels of angiotensin II and plasma IL-6 in different patients diagnosed with ARDS (acute respiratory distress syndrome) may also be utilized for inhibiting SARS-CoV-2 from accessing cellular ACE2 receptor." (PMID 32973505, 2020). "Macrophages, neutrophils, and T cells get activated through sustained elevation of cytokines including interleukin (IL)-1, IL-6, and tumor necrosis factor (TNF) alpha, resulting in type 2 pneumocyte apoptosis, and in some patients a path that leads to acute respiratory distress syndrome (ARDS)." (PMID 32946517, 2020). "A prospective study assessing interleukin (IL)-6 levels with or without CytoSorb therapy in acute respiratory distress syndrome (ARDS) patients found decreased IL-6 levels, but no survival benefit in the CytoSorb group." (PMID 33255912, 2020).
acute respiratory distress syndrome (continued). "In an animal model of acute respiratory distress syndrome (ARDS), a syndrome with an increase in IL-6, TNF, and neutrophils in the lungs, NAR supplementation can reduce neutrophils infiltration and oxidative stress, greatly reducing airway inflammation and lung injury." (PMID 33101291, 2020). "The overexpression of cytokines such as IL-2, IL-6, IL-7, GSCF, IP10, MCP1, MIP1A, and TNFα is followed by edema, which impairs oxygen exchange, and may lead to acute respiratory distress syndrome (ARDS) causing potential acute cardiac injury, secondary infection, and death." (PMID 32574317, 2020). "IL-6 and TNF-α may be the key contributors to virus mediated respiratory diseases, including Acute Respiratory Distress syndrome (ARDS) and acute lung injury." (PMID 32269562, 2020). "In fact, in different models of hemorrhagic shock, plasma, pulmonary and hepatic increases in IL-6 and MCP-1 were observed along with inflammation and lung injury, which may culminate in acute respiratory distress syndrome." (PMID 30657756, 2019). "Pulmonary infection is the most common cause of the acute respiratory distress syndrome (ARDS), that is associated with increased production and release of inflammatory cytokines/chemokines, such as tumor necrosis factor-α (TNF-α), interleukin-6 (IL-6), and IL-82." (PMID 27506372, 2016). "Severe COVID-19 and COPD involve cytokine storms (IL-6, TNF-α) and alveolar macrophage dysfunction, leading to acute respiratory distress syndrome (ARDS) and pulmonary fibrosis." (PMID 40565232, 2025). "Finally, in a mouse model of acute respiratory distress syndrome (ARDS) induced by poly (I:C) treatment, 5 mg/kg CBC was administered with an inhaler, and the therapeutic effect was confirmed by decreasing the expression of IL-6, IL-17, and IFN-γ." (PMID 39769302, 2024). "As an example, BALF-EVs increase interleukins IL-1β and IL-6, Tumor Necrosis Factor α (TNFα), and CC motif chemokine Ligand 2 (CCL2) in sarcoidosis disease and acute respiratory distress syndrome (ARDS)." (PMID 36768664, 2023). "Curcumin has been demonstrated to suppress the expression of inflammatory cytokines, including IL-6 and MCP-1, from lung tissue in a murine model of virus-induced acute respiratory distress syndrome (ARDS), potentially through a reduction in NF-κB activation." (PMID 37049389, 2023). "IL-6 and TNF-α play a crucial role in viral-mediated respiratory disorders such as acute respiratory distress syndrome (ARDS) and acute lung injury." (PMID 35328462, 2022). "Furthermore, they may increase levels of vascular endothelial growth factor (VEGF), monocyte chemotactic protein-1 (MCP-1), and interleukin-8 (IL-8) levels, as well as release of IL-6 and reduction of E-cadherin, eventually leading to acute respiratory distress syndrome (ARDS)." (PMID 34671410, 2021). "Additionally, this drug also reduces the levels of IL-6 in individuals with systemic lupus erythematosus and rheumatoid arthritis, thus hypothetically reducing the chance to develop cytokine storm and acute respiratory distress syndrome- (ARDS-) related complications." (PMID 33732744, 2021). "Furthermore, in a model of LPS-induced Acute respiratory distress syndrome (ARDS), treatment with pyridostigmine reduced the number of macrophages and lymphocytes in bronchoalveolar lavage fluid and suppressed levels of TNFα, IL-1β, IL-6, and IFN-γ." (PMID 34948222, 2021). "A recent study demonstrated that the raised levels of IL-6 and IL-10 were related with a high mortality in CAP, especially in severe CAP which could potentially increase the incidences of sepsis, lung injury and acute respiratory distress syndrome (ARDS)." (PMID 27846240, 2016). "In addition, Pro-inflammatory cytokines, mainly IL-6, are involved in the pathogenesis of acute lung injury (ALI), acute respiratory distress syndrome (ARDS), and cytokine storm-induced multi-organ damage in COVID-1952." (PMID 37045862, 2023).